ULK1 (unc-51 like autophagy activating kinase 1)
Description:
Serine/threonine-protein kinase involved in autophagy in response to starvation. Acts upstream of phosphatidylinositol 3-kinase PIK3C3 to regulate the formation of autophagophores, the precursors of autophagosomes. Part of regulatory feedback loops in autophagy: acts both as a downstream effector and negative regulator of mammalian target of rapamycin complex 1 (mTORC1) via interaction with RPTOR. Activated via phosphorylation by AMPK and also acts as a regulator of AMPK by mediating phosphorylation of AMPK subunits PRKAA1, PRKAB2 and PRKAG1, leading to negatively regulate AMPK activity. May phosphorylate ATG13/KIAA0652 and RPTOR; however such data need additional evidences. Plays a role early in neuronal differentiation and is required for granule cell axon formation. Also phosphorylates SESN2 and SQSTM1 to regulate autophagy. Phosphorylates FLCN, promoting autophagy. Phosphorylates AMBRA1 in response to autophagy induction, releasing AMBRA1 from the cytoskeletal docking site to induce autophagosome nucleation. Phosphorylates ATG4B, leading to inhibit autophagy by decreasing both proteolytic activation and delipidation activities of ATG4B.
Synonyms: ATG1; hATG1; ATG1A; UNC51; Unc51.1
Tractability: Small molecule: a structure with a bound ligand is known; a high-quality ligand is known; it belongs to a druggable protein family. PROTAC: it is named in the literature on targeted protein degradation; UniProt records ubiquitination sites on it; ubiquitination databases record sites on it; its protein half-life has been measured; a small molecule that binds it is known.
Target class: Kinase; Other protein kinase group; Other protein kinase ULK family; Enzyme; Protein Kinase
Chemical probes: ULK-101 (high quality)
Gene: Protein-coding gene on chromosome 12 (131,894,621 to 131,923,161, forward strand). Ensembl gene ENSG00000177169.
Subcellular location: Cytoplasm, cytosol; Preautophagosomal structure
Subcellular location (Human Protein Atlas): Cytosol
Pathways (Reactome):
Autophagy: Macroautophagy; Receptor Mediated Mitophagy
Vesicle-mediated transport: RAB GEFs exchange GTP for GDP on RABs; TBC/RABGAPs
Signal Transduction: Regulation of TNFR1 signaling
Gene Ontology:
Molecular function: GTPase binding; identical protein binding; protein binding; protein serine kinase activity; protein serine/threonine kinase activity; protein-containing complex binding; small GTPase binding; ATP binding; protein kinase activity
Biological process: autophagosome assembly; autophagy; cellular response to stress; intracellular protein localization; macroautophagy; negative regulation of cell population proliferation; negative regulation of protein-containing complex assembly; neuron projection development; peptidyl-serine phosphorylation; positive regulation of autophagy; protein autophosphorylation; regulation of macroautophagy; regulation of protein lipidation; axon extension; cellular response to nutrient levels; mitophagy; negative regulation of collateral sprouting; piecemeal microautophagy of the nucleus; protein phosphorylation; regulation of autophagy; regulation of tumor necrosis factor-mediated signaling pathway; response to starvation; reticulophagy; axonogenesis; signal transduction
Cellular component: Atg1/ULK1 kinase complex; autophagosome; autophagosome membrane; cytoplasm; cytosol; omegasome membrane; phagophore assembly site; phagophore assembly site membrane; phosphatidylinositol 3-kinase complex, class III; endoplasmic reticulum membrane; mitochondrial outer membrane; recycling endosome
Genetic constraint (gnomAD): Loss-of-function variants: 48 observed, 100.15 expected, observed/expected ratio (o/e) 0.48, 90% interval 0.38 to 0.61. The synonymous counts are far from expectation, so gnomAD's model fits this gene poorly and the ratio says little. Missense variants: 1,327 observed, 1,327.9 expected, observed/expected ratio (o/e) 1, 90% interval 0.95 to 1.05. Synonymous variants: 763 observed, 585.54 expected, observed/expected ratio (o/e) 1.3, 90% interval 1.23 to 1.38.
Homologues: Orthologues: macaque ULK1 (98% identical), pig ULK1 (91% identical), dog ULK1 (90% identical), mouse Ulk1 (90% identical), rat Ulk1 (89% identical), guinea pig ULK1 (88% identical), rabbit ULK1 (83% identical), tropical clawed frog ulk1 (70% identical), zebrafish ulk1b (59% identical), Drosophila melanogaster Atg1 (32% identical), Caenorhabditis elegans unc-51 (30% identical). Paralogues in human: ULK2 (52% identical), ULK3 (16% identical).
Diseases named in the same sentence as ULK1 in open-access papers:
ULK1 is named in the same sentence as 249 diseases in open-access papers, as found by Europe PMC text mining. Sharing a sentence is not in itself a finding about the gene and the disease. The quoted sentences say what the papers report.
breast cancer (85 papers, 2014 to 2026). A primary or metastatic malignant neoplasm involving the breast. "Co-culture experiments revealed that Fer-sEVs-educated macrophages significantly suppressed breast cancer cell migration, whereas ULK1-deficient Fer-sEVs restored migratory capacity." (PMID 41588464, 2026). "Mitophagy-initiating proteins such as ULK1 (Unc-51-like autophagy activating kinase 1) play a significant role in breast cancer, where a decreased expression of ULK1 is associated with breast cancer progression." (PMID 40214834, 2025). "In the context of breast cancer, ULK1 is strongly associated with disease progression and adverse prognostic outcomes, suggesting its potential as a novel therapeutic target and prognostic marker for breast cancer." (PMID 39664581, 2024). "In contrast, low ULK1 expression is associated with operable breast cancer progression and is an adverse prognostic marker of survival for patients." (PMID 35393404, 2022). "In breast cancer, low expression of ULK1 was found to associate with lymph node metastasis and poor patient survival." (PMID 31913283, 2020). "ULK1 expression was negatively associated with breast cancer progression and is a prognostic marker for breast cancer." (PMID 31913283, 2020). "Decreased ULK1 expression has been shown to be associated with cancer progression, suggesting ULK1 as a novel prognostic biomarker for breast cancer." (PMID 29783720, 2018). "For instance, increased expression of ULK1 is associated with poor prognosis in esophageal squamous cell carcinoma; however, in breast cancer, decreased ULK1 expression is associated with poor prognosis." (PMID 26561802, 2015). "Finally, the mammalian ortholog of Slmb, BTRC, has been shown to ubiquitinate ULK1 in breast cancer cells, leading to mitophagy deficiency and cancer cell metastasis." (PMID 40240351, 2025). "Phloretin could restrain cytotoxic autophagy by inhibiting the mTOR/ULK1 pathway, which improved the susceptibility of breast cancer cells to chemotherapies." (PMID 40064873, 2025). "ULK1 knockout mice demonstrate deficient mitophagy leading to breast cancer metastasis, especially to the bone, due to ROS-induced NLRP3 (nucleotide-binding oligomerization domain, leucine-rich repeat and pyrin domain-containing protein 3) inflammasome activation." (PMID 40214834, 2025). "Knockout of ULK1 led to mitophagy deficiency and promoted the metastasis of breast cancer cells, which implied that ULK1 might be a therapeutic target for breast cancer." (PMID 34585646, 2021). "As an example, conditional deletion of the gene coding for the ULK1/Atg1 interactor RB1CC1/FIP200 in mammalian epithelial cells restrains the growth of mammary carcinoma tumors induced by polyomavirus middle T antigen, associated with the induction of a prominent type I IFN response." (PMID 34459017, 2021). "ULK1 expression was recently linked to breast cancer metastasis." (PMID 31913283, 2020). "Furthermore, higher TRIB3 and ULK1 expression is associated with a poor prognosis in breast cancer while higher LAMP3 expression has been associated with lymph node positivity and hormone receptor negative breast cancers." (PMID 30248920, 2018). "Same study implied that Ulk1 mRNA upregulation is associated with poor prognosis of breast cancer." (PMID 28410240, 2017). "Intriguingly, the frequent presence of TRIM27 overexpression in breast cancer (BC) patients is associated with tumorigenesis, potentially through the inhibition of ULK1-mediated autophagy." (PMID 38803357, 2024). "RESULTS: In this study, we identify that sEVs derived from ferroptotic breast cancer cells (Fer-sEVs) are enriched in ULK1 and functionally suppress macrophage M2 polarization." (PMID 41588464, 2026). "CONCLUSION: Together, our findings reveal a novel ferroptosis-sEVs-mitophagy axis, in which hnRNPA2B1-mediated sEVs ULK1 delivery enhances mitophagy and reprograms macrophage polarization, ultimately restraining breast cancer migration." (PMID 41588464, 2026).
breast cancer (continued). "For instance, SBP-7455 was proved to inhibit the metastatic breast cancer cell growth through alleviating ULK1-mediated protective autophagy." (PMID 40064873, 2025). "It is reported that USP1 targets ULK1 and regulates canonical autophagy in breast cancer, which is consistent with our result in PDAC cells." (PMID 39814232, 2025). "Consistent with our observations for AMPK expression, knockdown of TRPV2 in breast cancer cells resulted in inhibition of ULK1 phosphorylation at serine 555, while cannabidiol treatment led to upregulation of ULK1 phosphorylation." (PMID 39334351, 2024). "ULK1/2 inhibits the actin assembly and hinders breast cancer cell contraction and migration, Selective splicing of genes in the intronic protein family, including ADD2, leads to alterations in cellular function during pathogenesis are associated with cancer." (PMID 39698112, 2024). "Conversely, an upregulation emerged in genes associated with the inhibition of breast cancer progression, including SIRT2, MST1, and ULK1, indicating the therapeutic potential of the peptide." (PMID 38272230, 2024). "The autophagy stimulated by icaritin via the activation of AMPK and ULK1 partially contributes to the inhibition of breast cancer proliferation." (PMID 36677797, 2023). "Similar to the MTA1-associated tamoxifen resistance, the AMPK-triggered MDR is also unique to doxorubicin-resistant breast cancer cells sustained by protective autophagy and activated ULK1." (PMID 36677797, 2023). "A previous study had demonstrated that ICT induced autophagy through upregulating the phosphorylation of AMPK and ULK1 in breast cancer cells." (PMID 36770781, 2023). "Trametinib has also been shown to upregulate the expression of autophagy promoter ULK1 in human breast cancer tissues." (PMID 36702816, 2023). "Resent document reported that ULK1 inhibits the metastasis of breast cancer cells by phosphorylating Exo70 protein." (PMID 35393404, 2022). "In breast cancer patients, low levels of ULK1 correlate with lymph node metastasis and poor survival." (PMID 35365653, 2022). "Several types of research have shown that ULK1 was under-expressed in some tumor tissues like breast cancer." (PMID 35963853, 2022). "For instance, it has been demonstrated that low expression of ULK1 in operable breast cancer tissues is a marker of poor prognosis." (PMID 36291728, 2022). "As downstream genes of PI3K-AKT signaling, ULK1 and RHOA mutations are rarely detected in breast cancer." (PMID 34007008, 2021). "For instance, miR-25 is a regulator of autophagy and cell death through its direct effects on the expression of ULK1 in breast cancer." (PMID 33572255, 2021). "Cancer Genome Atlas and Tissue Microarray analysis data shows that autophagy initiator protein, ULK1 was downregulated in breast cancer tissues." (PMID 34830816, 2021). "In breast cancer patients with high levels of Ulk1, a positive regulator of autophagy, clinical prognosis is improved." (PMID 33330501, 2020). "The relationship between ULK1 expression and the phosphorylation level of Exo70 on Ser89 in clinical breast cancer tissues was then examined using a commercial ULK1 antibody and our anti-phospho-Exo70-Ser89 antibody." (PMID 31913283, 2020). "Increased expression of protein kinase ULK1 was reported to negatively correlate with breast cancer metastasis." (PMID 31913283, 2020). "Together, these results demonstrated that ULK1 mediates the phosphorylation and inactivation of Exo70, resulting in the suppression of breast cancer cell motility and metastasis." (PMID 31913283, 2020). "In this study, we demonstrated that ULK1 suppressed the migration and invasion of human breast cancer cells." (PMID 31913283, 2020). "We propose a model that, under stress condition, ULK1 is activated and suppresses Exo70 to keep breast cancer cells dormant." (PMID 31913283, 2020).
breast cancer (continued). "Since our data showed that Exo70 phosphorylation by ULK1 inhibited breast cancer metastasis, we investigated the relationship between ULK1 expression and the phosphorylation levels of Exo70 in clinical breast cancer tissues." (PMID 31913283, 2020). "ULK1 phosphorylation of Exo70 on Ser47, Ser59, and Ser89 led to the suppression of breast cancer cell migration and invasion." (PMID 31913283, 2020). "To investigate the role of ULK1 in breast cancer metastasis, we examined the expression level of ULK1 in several human breast cancer cell lines with different metastatic potential." (PMID 31913283, 2020). "Downstream of PERK, ATF4 mediates hypoxia-induced breast cancer progression via regulation of tribbles homolog 3 (TRIB3), unc-51-like autophagy activating kinase 1 (ULK1), and lysosomal-associated membrane protein 3 (LAMP3)." (PMID 30248920, 2018). "Their activity was also detected in delphinidin-treated breast cancer cells; delphinidin promoted the activation of ULK1 and FOXO3a and this activation was enhanced by an increase in the dose of delphinidin." (PMID 29587684, 2018). "miR-25 inhibition led to autophagic cell death by directly increasing ULK1 expression in breast cancer cell." (PMID 26036635, 2015). "Previous studies have found that elevated ULK1 expression in human cancers is associated with poor clinical outcome, such as esophageal squamous cell carcinoma (ESCC) and breast cancer." (PMID 25714809, 2015). "Overall, our results not only indicate that ISL acts as a natural autophagy inducer to increase breast cancer chemosensitivity, but also reveal that miR-25 functions as a novel regulator of autophagy by targeting ULK1." (PMID 25026296, 2014). "Our study not only demonstrated that ISL is a natural autophagy inducer to increase breast cancer chemosensitivity but also elucidated the role of miR-25 as a novel regulator of autophagy modulation by targeting ULK1." (PMID 25026296, 2014). "Taken together, our data demonstrated that ISL induced the autophagic cell death of drug-resistant breast cancer cells both in vitro and in vivo and that miR-25 functioned as the primary autophagy-related modulator by targeting ULK1." (PMID 25026296, 2014). "Additionally, research in breast cancer has demonstrated that circCDYL promotes autophagy through the miR-1275-ATG7/ULK1 axis." (PMID 40476182, 2025). "ULK1 plays various roles in cancer progression, promoting the development of pancreatic, colon, high-grade serous ovarian, nasopharyngeal, and breast cancer." (PMID 39218913, 2024). "Similarly, in a cohort of breast cancer patients, those with tumors carrying high ULK1 mRNA expression were found to have a significantly shorter relapse-free survival." (PMID 38203816, 2024). "Moreover, miR-489 overexpression inhibits ULK1 to suppress autophagy, thus sensitizing breast cancer cells to DOX." (PMID 35211417, 2022). "Therefore, in the case of breast cancer, the activation of ULK1 can be used as an effective anti-cancer strategy." (PMID 36291728, 2022). "Although the underlying mechanism remain unclear, somatic mutation and overexpression of ULK1/2 has been observed in several solid tumors such as colon cancer, hepatocellular carcinoma (HCC) and breast cancer 36-38." (PMID 34345207, 2021). "Particularly, ULK1 agonist LYN-1604 was shown to interact with caspase 3 in breast cancer." (PMID 34830816, 2021). "In addition, fluoxetine, a selective serotonin reuptake inhibitor was shown to inhibit breast cancer growth by inducing ULK1/autophagy-mediated apoptosis." (PMID 34830816, 2021). "Thus, this study identifies TRPM8 as a novel regulator of basal autophagy in cancer cells acting by interacting with AMPK, which in turn activates AMPK to activate ULK1 in a coordinated cascade of TRPM8-mediated breast cancer progression." (PMID 33344232, 2020). "Phosphorylation of Exo70 by ULK1 inhibits the metastasis of breast cancer cells." (PMID 31913283, 2020).